SMOX (spermine oxidase)
Description:
Flavoenzyme which catalyzes the oxidation of spermine to spermidine. Can also use N(1)-acetylspermine and spermidine as substrates, with different affinity depending on the isoform (isozyme) and on the experimental conditions. Plays an important role in the regulation of polyamine intracellular concentration and has the potential to act as a determinant of cellular sensitivity to the antitumor polyamine analogs. May contribute to beta-alanine production via aldehyde dehydrogenase conversion of 3-amino-propanal.
Synonyms: PAO-1; PAOh1; C20orf16; SMO; FLJ20746; dJ779E11.1; PAO; MGC1010; PAO1; PAOH
Tractability: Small molecule: a structure with a bound ligand is known. PROTAC: ubiquitination databases record sites on it; a small molecule that binds it is known.
Target class: Enzyme; Oxidoreductase
Chemical probes: JNJ-9350 (high quality)
Gene: Protein-coding gene on chromosome 20 (4,120,980 to 4,187,748, forward strand). Ensembl gene ENSG00000088826.
Subcellular location: Cytoplasm (Isoform 1); Nucleus; Cytoplasm (Isoform 4); Cytoplasm (Isoform 6)
Subcellular location (Human Protein Atlas): Nucleoplasm; Cytosol; Nuclear membrane; Vesicles
Pathways (Reactome):
Metabolism: Interconversion of polyamines; PAOs oxidise polyamines to amines
Gene Ontology:
Molecular function: spermine oxidase activity; oxidoreductase activity; polyamine oxidase activity
Biological process: polyamine catabolic process; polyamine biosynthetic process; spermine catabolic process; xenobiotic metabolic process
Cellular component: cytosol; nuclear membrane; nucleoplasm; cytoplasm; nucleus
Genetic constraint (gnomAD): Loss-of-function variants: 19 observed, 42.75 expected, observed/expected ratio (o/e) 0.44, 90% interval 0.31 to 0.65. The upper end of that interval is the gene's LOEUF score, 0.65, which puts it in group 2 of 6, group 1 being the genes least tolerant of losing a copy. Missense variants: 509 observed, 702.2 expected, observed/expected ratio (o/e) 0.72, 90% interval 0.67 to 0.78. Synonymous variants: 259 observed, 279.02 expected, observed/expected ratio (o/e) 0.93, 90% interval 0.84 to 1.03.
Homologues: Orthologues: chimpanzee SMOX (99% identical), macaque SMOX (99% identical), dog SMOX (96% identical), rat Smox (96% identical), pig SMOX (96% identical), mouse Smox (95% identical), guinea pig SMOX (95% identical), rabbit SMOX (95% identical), rat RGD1564480 (89% identical), tropical clawed frog smox (70% identical), zebrafish smox (69% identical), Drosophila melanogaster CG8032 (33% identical), and 8 more. Paralogues in human: PAOX (37% identical), KDM1A (20% identical), KDM1B (19% identical), IL4I1 (18% identical), MAOB (17% identical), MAOA (17% identical), PPOX (13% identical).
Diseases named in the same sentence as SMOX in open-access papers:
SMOX is named in the same sentence as 109 diseases in open-access papers, as found by Europe PMC text mining. Sharing a sentence is not in itself a finding about the gene and the disease. The quoted sentences say what the papers report.
colorectal cancer (15 papers, 2016 to 2026). A primary or metastatic malignant neoplasm that affects the colon or rectum. "High SMOX expression has been implicated in gastric cancer, hepatocellular carcinoma, and colorectal cancer." (PMID 40823069, 2025). "A study involving patients with colorectal cancer has revealed that SMOX overexpression could be caused by the activation of the transcription factor C/EBPβ, which is involved in the regulation of inflammation and immunity, rather than the ETBF infection." (PMID 31467634, 2019). "Thus, it is possible that the increased SMOX gene expression and enzyme activity make the greatest contribution to the oxidative stress damage caused by polyamine catabolism in colorectal cancer." (PMID 27433286, 2016). "To explore the potential role of SMOX in the development of colorectal cancer, we treated colorectal cancer cells with different concentrations of Q3ME to detect the mRNA and protein expression of related genes in the polyamine metabolic pathway." (PMID 38617002, 2024). "Q3ME decreased the levels of polyamines (spermine and spermidine) in colorectal cancer cells, and reduced the protein expression of SMOX, an enzyme responsible for converting spermine to spermidine." (PMID 38617002, 2024). "The present study aims to explore the biologic function and expression patterns of SMOX in colorectal cancer (CRC), the third most common type of cancer worldwide." (PMID 35327428, 2022). "Western blot analysis was performed to confirm the successful immune precipitation of the transcription factor NF-κB p65 which binds to SMOX in colorectal cancer cells." (PMID 36353478, 2022). "BFT induces spermine oxidase (SMO)-mediated DNA damage in T84 human colorectal cancer cells in vitro and ETBF infection increases SMO expression in colon epithelial cells in mice." (PMID 32038097, 2020). "Our data showed increased expression of SMOX gene at all stages of colorectal cancer, this tendency being more pronounced at the early stages." (PMID 27433286, 2016). "This suggests that Q3ME may induce apoptosis in colorectal cancer cells by decreasing intracellular spermidine level through the inhibition of SMOX." (PMID 38617002, 2024). "Bacteroides fragilis in the intestines of patients with colorectal cancer produce a variety of toxic metabolites such as β-glucuronidase, spermine oxidase, reactive oxygen species, reactive nitrogen species, and nitroso compounds, which can induce DNA damage and promote colorectal cancer." (PMID 34267748, 2021). "Elevated expression of SMOX was shown in prostate and colorectal cancers." (PMID 31467634, 2019). "The results of coexpression analysis coupled to ENCODE ChIP-Seq data strongly suggest c-Myc and C/EBPβ as regulators of the expression of key enzymes of polyamine metabolism that are upregulated in colorectal cancer: SMOX, AZIN1, MTAP, SRM, AMD1, ODC1, and AGMAT." (PMID 27433286, 2016). "Similarly, the expression of SMOX is upregulated in gastric, lung, breast, prostate, and colorectal cancers, which may serve as a prognostic indicator for colon cancer." (PMID 40040695, 2025). "However, it has been suggested that genetically determined SMOX activity does not correlate with the risk of childhood neuroblastoma or adult cancers, including gastric, lung, breast, prostate, and colorectal cancers." (PMID 40040695, 2025). "SMOX catalyzes the conversion of spermine into spermidine, and is a source of cancer-related reactive oxygen species (ROS) and is up-regulated in a wide range of cancers, including colorectal cancer (CRC), non-small cell lung cancer (NSCLC), and gastric cancer." (PMID 40225858, 2025). "To understand the clinical significance of SMOX and SUCLG2, we focused on colorectal cancer (CRC) for further analyses and predicted and constructed a potential competing endogenous RNA (ceRNA) network." (PMID 40699864, 2025). "However, our study is the first to report the putative involvement of SAT1, SMOX, SRM, and RR M2 in colorectal cancer." (PMID 31417867, 2019).
colorectal cancer (continued). "These analyses reveal the unknown effect of SMOX, SMS, and SRM genes in colorectal cancer." (PMID 31417867, 2019).
gastric cancer (12 papers, 2020 to 2025). A primary or metastatic malignant neoplasm involving the stomach. "Mice deficient in SMOX showed dramatically reduced levels of gastric spermidine and H. pylori-induced inflammation, suggesting that the SMOX gene is associated with an increased risk of human gastric cancer." (PMID 40225858, 2025). "miR-124 through the inhibition of SMOX-mediated DNA damage in the etiology of H. pylori-associated gastric cancer." (PMID 36314013, 2022). "In these studies, the expression of SMOX, induction of DNA damage, and development of cancerous lesions was associated with a strain of H. pylori that was more likely to lead to gastric cancer vs. that of the low-cancer-risk strain." (PMID 35893120, 2022). "Biopsies of H. pylori infected individuals with gastritis demonstrated that elevated levels of SMOX expression in the samples were associated with increased risk of developing gastric cancer." (PMID 35893120, 2022). "In Helicobacter pylori infections, the expression of SMOX is associated with chronic inflammation and increased risk of developing gastric cancer." (PMID 35893120, 2022). "Spermine oxidase (SMOX) is potentially associated with oxidative DNA damage in gastric cancer by catabolizing polyamine spermine and producing H2O2." (PMID 34393804, 2021). "Six candidate variants identified, of which 2 have previously characterized tumorigenic roles: (a) Increased expression of SMOX is associated with gastric cancer, and (b) SYTL3 encodes proteins which interact with RAB27 and deregulation of this pathway is associated with bladder cancer." (PMID 32201880, 2020). "Specifically, an increase in SMOX activity parallels the progression of prostate, liver and gastric carcinoma, while high polyamine catabolic enzyme levels have been positively related to a good prognosis in breast cancer patients." (PMID 36755974, 2023). "The induction of SMOX by Helicobacter pylori infection mediates H. pylori-induced gastric inflammation, DNA damage, and activation of β-catenin signaling in gastric cancer." (PMID 36046649, 2022). "Given this, we contend that inhibition of SMOX activity and/or scavenging acrolein may prevent gastric cancer in H. pylori-infected patients." (PMID 39523394, 2025). "Spermine oxidase (SMOX) is a polyamine metabolizing enzyme that catalyzes the conversion of spermine to spermidine and is known to mediate Helicobacter pylori-induced gastric cancer." (PMID 36046649, 2022).
neuroblastoma (6 papers, 2016 to 2025). Neuroblastoma (NB) is the most common solid, extracranial childhood tumor. "SMOX has been reported as a source of induced reactive oxygen species (ROS) associated with neuroblastoma, gastric, lung, breast, prostate and colon cancers, implying that inhibition of SMOX could be a target for chemoprevention." (PMID 34465810, 2021). "Since the SMOX genetic instrument, rs1741315, explained 5 to 6 times more variance of SMOX expression in newborns than in adults, we used MR to test the causal association between SMOX expression and neuroblastoma, a pediatric cancer in which SMOX has been reported to play a role." (PMID 34465810, 2021). "It is worth noting that SMOX ectopic expression in neuroblastoma cells increases oxidative DNA damage thus inducing apoptosis." (PMID 38617002, 2024). "Previously, we reported that HIV-Tat elicits spermine oxidase (SMO) activity upregulation through NMDA receptor (NMDAR) stimulation in human SH-SY5Y neuroblastoma cells, thus increasing ROS generation, which in turn leads to GSH depletion, oxidative stress, and reduced cell viability." (PMID 26895301, 2016). "As this directly aligns with the effects of SMOX upregulation, the compounds were assessed for the ability to inhibit cytotoxicity in SH-SY5Y neuroblastoma cells exposed to glutamate." (PMID 36135832, 2022).
breast cancer (5 papers, 2016 to 2025). A primary or metastatic malignant neoplasm involving the breast. "Four high-risk independent prognostic factors (OAZ1, SRM, SMOX, and SMS) were validated as being upregulated in breast cancer tissues." (PMID 40823069, 2025). "SMO was found to be elevated in both prostate adenocarcinoma and prostatic intraepithelial neoplasia whereas breast cancer showed SMOX underexpression at both mRNA and protein levels." (PMID 27433286, 2016).
Cerebral ischemia (4 papers, 2022 to 2025). Restriction of arterial blood supply to the brain associated with insufficient oxygenation to support the metabolic requirements of the tissue. "In rat MCAO models, a significant increase in SMOX expression occurred in neurons and downregulation of SMOX significantly reduced cerebral ischemia injuries." (PMID 36358946, 2022). "SMOX induction has been reported in diabetic retinopathy as well as in brain ischemia; in these pathological conditions, the upregulation of SMOX seems to be responsible for neuron damage." (PMID 35885061, 2022). "Studies have indicated the role of SMOX signaling in neuroprotection through various pathways, including antioxidant signaling via Nrf2 in experimental stroke, neuroinflammation in cerebral ischemia via IL6/TNFa, and miR-340-5p/Smurf1 signaling in spinal cord injury." (PMID 40001462, 2025).
diabetes (4 papers, 2020 to 2024). "Our results demonstrate a crucial role for the SMOX pathway as one of the major mechanisms associated with diabetes-induced neuronal damage and dysfunction in the retina." (PMID 31991839, 2020). "While we were unable to examine changes in vimentin expression in diabetic retinas through immunofluorescence, the data we gathered provided compelling evidence of the impact of SMOX inhibition on glial cell health in the context of diabetes." (PMID 39768141, 2024). "Utilizing ERG analysis, we investigated the impact of SMOX inhibition on diabetes-induced functional changes in the retina." (PMID 31991839, 2020). "Utilizing MDL 72527, the present study investigated the impact of SMOX blockade in reducing diabetes-induced retinal neurodegeneration and dysfunction." (PMID 31991839, 2020). "Our current study is the first report examining the impact of SMOX inhibition in preventing diabetes-induced neurodegeneration in the retina." (PMID 31991839, 2020). "Targeting SMOX signaling may provide a potential strategy for reducing retinal neuronal damage and preserving vision in diabetes." (PMID 39768141, 2024). "The involvement of SMOX in diabetes-induced retinal neuronal damage is completely unknown." (PMID 31991839, 2020). "Diabetes-induced changes in neuronal-specific class III tubulin (Tuj-1), synaptophysin, glutamine synthetase, and vimentin were attenuated in response to SMOX inhibition." (PMID 39768141, 2024). "The present study reports for the first time, the impact of blocking spermine oxidase, using systemic treatment with MDL 72527, in limiting diabetes-induced neurodegeneration in the retina." (PMID 31991839, 2020). "However, since the focus of our present study is solely on diabetes-induced neurodegeneration in the retina, we have not evaluated these changes in response to SMOX inhibition." (PMID 31991839, 2020).
diabetic retinopathy (4 papers, 2022 to 2024). "Among PA oxidases, SMOX was reported to be involved in causing neurovascular damage in the retina and was proposed as a therapeutic target for neurodegeneration in diabetic retinopathy." (PMID 35885061, 2022). "Our findings suggest that SMOX inhibition holds great promise as a therapeutic avenue for treating diabetic retinopathy in patients with this debilitating condition." (PMID 39768141, 2024). "Recent studies from our lab investigated the impact of SMOX inhibition via MDL 72527 treatment in the models of retinal excitotoxicity and diabetic retinopathy (DR), and indicated that SMOX inhibition is capable of suppressing retinal inflammation and reducing neuronal damage." (PMID 36552864, 2022). "Previous studies from our laboratory demonstrated that spermine oxidase (SMOX, a member of the polyamine oxidase family) inhibition using MDL 72527 reduced neurodegeneration in models of retinal excitotoxicity and diabetic retinopathy." (PMID 35216248, 2022). "Previous studies from our lab have shown that MDL 72527, a pharmacological inhibitor of spermine oxidase (SMOX), is protective against neurodegeneration and inflammation in the models of diabetic retinopathy and excitotoxicity." (PMID 36552864, 2022).
liver cancer (4 papers, 2022 to 2026). An epithelial or non-epithelial malignant neoplasm that arises from the liver. "SMOX also plays a role in regulating the phosphatidylinositol 3′-kinase/protein kinase B signaling pathway in liver cancer cells, affecting cancer cell growth." (PMID 40699864, 2025). "Increased expression of SMOX is frequently found in lung, prostate, colon, stomach and liver cancer models, and the enzyme also appears to play a role in neuronal dysfunction and vascular retinopathy." (PMID 35452470, 2022).
lung carcinoma (4 papers, 2017 to 2025). "First, in the GSE46539 lung adenocarcinoma cohort, the expression level of PSMC6, SMOX, and SMS was higher in the tumor samples than in the normal samples, which was consistent with the previous result in TCGA lung cancer samples." (PMID 38650895, 2024). "It has been used on lung cancer cells showing that it is able to reduce cell growth in vitro and PAs biosynthesis and to induce SAT1 and SMOX activities supporting the feasibility of the approach." (PMID 36755974, 2023).
Stroke (4 papers, 2020 to 2025). Sudden impairment of blood flow to a part of the brain due to occlusion or rupture of an artery to the brain. "Especially regarding stroke, the level of protein-conjugated acrolein (PC-Acro) in plasma was increased, and the multiplied value of spermine oxidase (SMOX) and acetylpolyamine oxidase (PAOX) was nearly parallel with the size of brain infarction." (PMID 37511605, 2023). "Expression of spermine oxidase was found to be increased in a rat model of stroke, and this increase has been shown to be positively correlated with the severity of brain injury following excitotoxic damage." (PMID 32256357, 2020).
hepatocellular carcinoma (3 papers, 2017 to 2025). A malignant tumor that arises from hepatocytes. "SMOX expression has been found to gradually increase in normal liver, chronic hepatitis, and hepatocellular carcinoma, and it is linked to hepatocellular carcinoma prognosis." (PMID 40699864, 2025). "In this report, we investigated the physiological functions of SMOX in liver cells using human hepatocellular carcinoma derived HepG2 cells." (PMID 29093526, 2017).
colitis (2 papers, 2018 to 2022). Inflammation of the colon. "To now determine the role of SMOX in another infectious model of the gastrointestinal tract, we infected WT and Smox−/− mice with C. rodentium, the rodent equivalent of enteropathogenic Escherichia coli that causes colitis in mice." (PMID 29922289, 2018). "We next treated WT and Smox−/− mice with DSS to assess the role of SMOX in a second model of experimental colitis." (PMID 29922289, 2018). "Altogether, these results support that the constitutive expression of SMOX, which can be augmented under specific conditions, is critical for the maintenance of spermine to spermidine flux in the colon and thus plays a role in the pathophysiology of colitis." (PMID 29922289, 2018). "Thus, SMOX contributes to the immunopathogenesis of C. rodentium infection, but is protective in DSS colitis, indicating the divergent effects of spermidine." (PMID 29922289, 2018).
inflammatory bowel disease (2 papers, 2018 to 2021). A spectrum of small and large bowel inflammatory diseases of unknown etiology. "In addition, we reported that SMOX can be upregulated in humans with inflammatory bowel disease." (PMID 29922289, 2018).
injury (2 papers, 2020 to 2025). Damage inflicted on the body as the direct or indirect result of an external force, with or without disruption of structural continuity. "The present study provides compelling evidence that the age-dependent upregulation of spermine oxidase (SMOX) plays a critical role in modulating oxidative stress, neuro-inflammation, and neuronal vulnerability following traumatic brain injury." (PMID 40563341, 2025).
prostate carcinoma (2 papers, 2011 to 2021). A carcinoma that arises from epithelial cells of the prostate gland. "There is reported increased expression of spermine oxidase (enzyme that converts spermine to spermidine) in prostate cancer, which could explain the slight elevation of spermidine shown in this study and by others." (PMID 33514438, 2021).